ITPKB (inositol-trisphosphate 3-kinase B)
Diseases named in the same sentence as ITPKB in open-access papers (continued):
Sharing a sentence is not in itself a finding about the gene and the disease.
cancer (12 papers, 2015 to 2025). A tumor composed of atypical neoplastic, often pleomorphic cells that invade other tissues. "Its target gene, ITPKB, may be directly regulated by miR-375 and play a crucial role in cancer development." (PMID 40971592, 2025). "Importantly, the authors showed that downregulation of ITPKB, sensitized cisplatin-resistant cancer cells to cisplatin treatment both in vitro and in vivo." (PMID 33198256, 2020). "Co-occurrence of genetic mutations in tumors with PARP1 alterations involved some genes that were enriched in transcriptional misregulation in cancer pathways (e.g., H3F3A, HIST3H3) and calcium signaling pathways (e.g., ITPKB, RYR2)." (PMID 34531868, 2021). "For example, AGTR1, GRIN2A, ITPKB, and SLC8A3 were repressed by hypermethylation in six cancer types, and ADCY4, ADCY8, BST1, and PRKCB were inhibited by hypermethylation in five cancer types." (PMID 28060724, 2017). "Alterations in the Ca2+ signaling pathway were observed in nine cancer types and AGTR1 GRIN2A (Glutamate Ionotropic Receptor NMDA Type Subunit 2A), ITPKB (Inositol-Trisphosphate 3-Kinase B), and SLC8A3 (Solute Carrier Family 8 Member A3) were repressed by hypermethylation in six of them." (PMID 32629766, 2020). "Besides, ITPKB and CCAT1 had been generally proved to participate in cancer cell proliferation." (PMID 29190961, 2017). "Recent work has shown that ITPKB is recurrently altered in human cancers and represents a significant regulator of AML cell proliferation and survival, though alone ITPKB dysfunction does not appear to promote leukemic transformation." (PMID 26384344, 2015).
neurodegenerative disease (3 papers, 2022 to 2025). A disorder of the central nervous system characterized by gradual and progressive loss of neural tissue and neurologic function. "ITPKB is linked to various neurodegenerative diseases, including AD, due to its role in synaptic function." (PMID 40287491, 2025). "Among these genes of neurodegenerative diseases, we observed that the NAP1L5 expression was significantly positively correlated with NEUROD6 and NRN1, whereas correlated with negatively CD163, ITPKB, and AQP1." (PMID 36568274, 2022). "While there is no concordance in the direction of the ITPKB effect in PD or AD, this kinase has a reported impact on both of the most common neurodegenerative diseases." (PMID 36768321, 2023).
ITPKB also shares sentences with these, for which no sentence is quoted: Autoimmunity (2 papers); anemia (1); blood cancers (1); cataract (1); COVID-19 (1); epileptic syndromes (1); familial Alzheimer disease (1); gastric tumor (1); Hodgkins lymphoma (1); lung adenocarcinoma (1); lung squamous cell carcinoma (1); MALT lymphoma (1); medulloblastoma (1); myeloma (1); Obesity (1); osteosarcoma (1); ovarian carcinoma (1); ovarian tumors (1); Parkinson’s (1).